GZMB (granzyme B)
Diseases named in the same sentence as GZMB in open-access papers (continued):
Sharing a sentence is not in itself a finding about the gene and the disease.
tumor (continued). "To analyze whether probe H5 could detect ongoing GzmB-mediated killing of tumor cells, we treated all samples with probe H5 (30 min, r.t.)and surface markers for epithelial cells (EpCAM), leukocytes (CD45), and cytotoxic T lymphocytes (CD8) before flow cytometry analysis." (PMID 35501326, 2022). "Therefore, a downregulated ratio of Tregs to CTLs at the tumor site could probably mediate increased granzyme B secretion and consequently enhance the T cell-mediated tumor growth inhibition." (PMID 36358638, 2022). "Moreover, the proportions of interferon γ (IFNγ) and granzyme B (GzmB)-producing CD8+ T cells were significantly increased in KO mice than that in WT mice, suggesting that compared with WT mice, the anti-tumor immunity was enhanced in the FcγRIIB deficient mice." (PMID 34976216, 2022). "Therefore, we detected the expression of granzyme B in LUAD tumour xenografts by IF assay." (PMID 35971127, 2022). "Importantly, the outer cells with membrane blebs were also positive in GZMB, suggesting the GZMB might be responsible for the death of outer tumor cells." (PMID 35436988, 2022). "Thus, Tregs encountering cytotoxic T cells or NK cells in the tumor microenvironment could use the same mechanism to induce their apoptotic death by granzyme B and perforin, thus suppressing the immune response." (PMID 35563441, 2022). "Albeit gzmB activates apoptosis by direct or indirect mitochondrial-mediated caspase activation, it has been shown that these pathways are dispensable for the elimination of tumour cells mediated by gzmB of Tc and NK cells, both in mouse and human models, in vivo and in vitro." (PMID 35651603, 2022). "Thus, we measured granzyme B and perforin levels in the tumor tissue using flow cytometry." (PMID 37693071, 2022). "Furthermore, IL-15 production by CD24+CD29+EpCAM+ epithelial cells was higher in PyMT tumors than in normal tissue and the deletion of tumor-expressed IL-15 resulted in a decrease of ILC1s, a downregulation of granzyme B and C expression, and a reduced tumor control." (PMID 36115839, 2022). "The decrease in the number of Granzyme B+ NK cells in the blood of all mice receiving gene therapies may potentially be attributed to the cells trafficking to other anatomical regions, including the tumor after vascular normalization had occurred." (PMID 35203573, 2022). "The results showed that although granzyme B is a secretory protein, most of it was retained in the tumor site (93.81%) rather than distributed throughout the circulation, suggesting the feasibility of in vivo imaging of granzyme B released by CTLs in the tumor." (PMID 35788116, 2022). "Therefore, PET of granzyme B may facilitate direct visualization of tumor killing by immune cells, suggesting that it is a reliable biomarker of tumor responses to immunotherapy." (PMID 35788116, 2022). "Moreover, arginine depletion in the TME promotes the accumulation of CD11b+Gr1+ MDSCs that suppress antitumor functions of T cells, and pharmacological inhibition of arg-1 suppresses the activity of G-MDSCs, restoring the production of IFN-γ and granzyme B by T cells and reducing tumor growth." (PMID 36713558, 2022). "Consistent with the MC38 tumor model, RagD-deficient antigen-specific CD8+ T cells failed to suppress tumor growth, as well as a decrease in the proportions of IFN-γ+ TNF-α+ polyfunctional and IFN-γ-secreting, TNF-α-secreting and GZMB-secreting subpopulations from CD8+ TILs." (PMID 33883257, 2021). "Researches indicated that exosomes from either the in vitro culture of tumor cells or the peripheral blood of tumor-bearing patients could educate CD4+CD25- T cell into iTregs with elevated granzyme B level, which effectively suppressed the immune responses against tumors." (PMID 33868318, 2021).
tumor (continued). "On the other hand, a higher CD8 + Granzyme B+ T cell intra-tumoral/peritumoral (I/P) ratio was observed in CD patients, suggesting their preferential infiltration of tumor masses where they might be regarded as exerting a direct cytotoxic activity against metastatic UM cells." (PMID 33947438, 2021). "Therefore, we analyzed granzyme B expression in CD8+ cells using tumor samples." (PMID 34832863, 2021). "Therefore, targeting granzyme B in ECM could be a promising strategy to attenuate tumor angiogenesis and mitigate the inflammatory response in TME." (PMID 33868318, 2021). "Some important immune-associated genes, such as granzyme B, IFN-γ, IL-2, IL-12, FoxP3 and STING, are regulated via epigenetic mechanisms in immune or/and cancer cells, as are immune checkpoint molecules (PD-1, CTLA-4, TIM-3, LAG-3, TIGIT) expressed by immune cells and tumor-associated stromal cells." (PMID 34930302, 2021). "Moreover, the degree of connectivity of GPX4, GZMA, and GZMB in the PPI network above was 4, 4, and 10, respectively, suggesting that GZMB may indeed be involved in tumor growth and progression in CC patients." (PMID 34837692, 2021). "Furthermore, tumors from mice treated with combined therapy have significantly higher granzyme B levels, indicated that anti-PD-1 therapy combined with GM-CSF might promote the anti-tumor effect of TILs." (PMID 34051805, 2021). "Typically, clinical assessment of therapy response is based on tumor size reduction, whether granzyme B imaging peptides will be able to distinguish between progressive disease and partial response is difficult to determine from studies based on tumor growth inhibition." (PMID 33713000, 2021). "Additionally, CAR T cell‐released GzmB triggers GSDME‐mediated pyroptosis in target tumour cells." (PMID 34590363, 2021). "The lysis of mHsp70+ tumor cells by NK cells could be attributed to granzyme B." (PMID 34079819, 2021). "In addition, PD1, CTLA4, LAG3, TIM3 and GZMB were common inhibitory receptors (IRs) in the tumor microenvironment, which could inhibit immune responses and even cause immune escape or tolerance after binding with corresponding ligands." (PMID 34721537, 2021). "Therefore, we quantified granzyme B production in the tumor as a means of examining the successful cytotoxic activity of CTLs and we observed a notable increase in tumors of probiotic-fed mice, where levels of granzyme B approximately doubled." (PMID 32033490, 2020). "Interestingly, the expression of DCK was associated with the gene markers like CCR8, STAT5b, and TGFB1 of Tregs, and PD–1, CTLA–4, LAG3, TIM–3, and GZMB of exhausted T cells after adjusting tumor purity, revealing that increased expression of DCK was associated with immunosuppression in HCC." (PMID 32690026, 2020). "First, γδ T cells could kill tumor cells directly through secreting perforin and granzyme B." (PMID 33664732, 2020). "Lactic acid repressed the number of CTL that performed lytic granule exocytosis (degranulation) in tumor cell co-culture, and, additionally impaired the quality of the response, as judged by the reduced intensity of degranulation and lower secretion of cytotoxins (perforin, granzyme B, granzyme A)." (PMID 33364193, 2020). "Upregulated expression of GM-CSF and granzyme B in PMN-MDSC could be associated with their capability of recruiting neutrophils in the TME, which potentially increases tumor-associated neutrophils, and releasing cytolytic molecules to kill immune cells that positively regulate anti-tumor immunity." (PMID 33312958, 2020). "In line, genetical or antibody-mediated depletion of CD8+ T-cells in PI3Kγ−/− mice caused a reduced tumor control but no alterations in proliferation or production of IFNγ or GzmB of PI3Kγ-deficient T-cells isolated from either naïve or tumor bearing mice have been observed ex vivo." (PMID 33552053, 2020).
tumor (continued). "We demonstrated that MDSCs express perforin and GzmB, and that these effector molecules contribute to the MDSCs ability to promote tumor progression in multiple ways, namely enhanced invasive capability of tumor cells, enhanced tumor growth, and the ability to influence CD8+ T-cell responses." (PMID 31212684, 2019). "In an OVA-expressing tumor model, Wnt1-overexpression by DCs was associated with reduced T cell receptor stimulation, granzyme B secretion and cytotoxicity by CD8+ T cells, whereas conditional knockout of LRP5/LRP6 in CD11c+ cells resulted in an increase in granzyme B production by CD8+ T cells." (PMID 31781093, 2019). "Moreover, in NSCLC, a dormant tumor-infiltrating lymphocytes (TIL) signature characterized by low activation (Granzyme B) and proliferation markers (Ki-67) in CD3 + TILs was also recently demonstrated to be associated with survival benefit in patients treated with ICI." (PMID 30709424, 2019). "However, as NK cells are also capable of exerting tumor cell killing activity by Granzyme B and Perforin expression, we next determined whether RGMB actually augments the repressive activity of sCTLA-4 on co-stimulation of CD8+ T cells." (PMID 31061392, 2019). "Moreover, the proportion of CD3+CD8+ T cells among CD45+ cells increased in tumor and paracancerous tissue from Fgl2−/− mice, accompanied by elevated surface expression of CD107a and production of granzyme B, which promoted BNL tumor-cell killing in ex vivo assays." (PMID 31409352, 2019). "These include increased shift toward M2 protumoral phenotype in tumor-associated macrophages, a reduced granzyme B-producing CD3+CD8+GzmB+ T cells, increased circulating VEGF and increased cancer stem cells markers on Oct4+ and CD44+CD133+ expressing TC1 tumor cells." (PMID 30811514, 2019). "In addition, depletion of B7-H4 could help restore CD8+ T anti-tumor immunity by elevating the expression and secretion levels of CD107a, granzyme A, granzyme B, perforin and IFN-γ." (PMID 29113351, 2017). "Therefore, we analysed CTL populations in the tumours and found that effector memory CTLs were the majority of the population and had the highest expression of perforin and granzyme B, suggesting that effector memory CTLs are critical for IL-1β secretion in the tumour model." (PMID 28537251, 2017). "Moreover, the upregulation of granzyme B expression by anti-CAIX CAR T cells secreting anti-PD-L1 provides strong evidence for the restoration of killing activity of CAR T cells at the tumor site, and the decrease in Ki67 staining shows the reduction in the proliferation of tumor cells." (PMID 27145284, 2016). "In addition, the frequency of granzyme B in tumor-infiltrating CD3+CD56+ NKT-like cells was also lower than that of the counterparts in non-tumor tissues, suggesting that the cytokine and cytotoxic molecule production of tumor-infiltrating CD3+CD56+ NKT-like cells were decreased." (PMID 27409423, 2016). "Murine models of lung AC have demonstrated that Tregs may inhibit CD8+ T cell-mediated anti-tumor immunity, with the depletion of Tregs resulting in tumor cell death and elevated levels of granzyme A, granzyme B, perforin and IFN-γ in infiltrating CD8+ T cells at early stages of tumorigenesis." (PMID 27784305, 2016). "Importantly the results have implicated that the expression of GZMB was upregulated in CIKIL-2 compared to CIKIL-15, which negatively correlated with the expression profiles of miR-199a-5p and miR199b-5p and suggested the enhance tumor cytotoxicity of CIKIL-2." (PMID 25826780, 2015). "Deletion of AMPK in CD8+ T cells results in decreased production of IFNγ and Granzyme B. Mechanistically, AMPK deficiency in T cells enhances serine/threonine protein phosphatase activity upon activation, thus leading to elevated cell death and impaired anti-tumor functions." (PMID 25760243, 2015).
tumor (continued). "In addition to mediating innate and adaptive anti-tumor immunity, DCs can have direct tumoricidal activity through perforin, granzyme B, and TNF-related apoptosis-inducing ligand (TRAIL); and promote innate anti-tumor immune responses through NK cell cytotoxic activity and IFN-γ production." (PMID 26690204, 2015). "In addition, granzyme B, produced by CTLs, exerts a tumor suppressive effect." (PMID 25009582, 2014). "In addition, the CTLs produced granzyme B, which exerted a tumor suppressive effect." (PMID 25009582, 2014). "The granzyme B-inhibitory serpin proteinase inhibitor-9 (PI-9) has also been identified inside exosomes and could also play an important role in the resistance of tumor cells to NK cells." (PMID 24400010, 2013). "Given the observation of PSK and docetaxel-induced TIL enhancement, we further analyzed whether any changes in IFN-γ, IL-2, TNF-α, TGF-β, perforin, granzyme B and FoxP3 mRNA expression in the tumor micro-environment could be observed in response to the treatments." (PMID 22159900, 2012). "However, the significance of this property has been largely ignored, until recently two studies have provided compelling evidence that cytotoxic CD4+ T cells developed in a lymphopenic environment can eradicate established melanoma as a result of direct killing of the tumor cells through granzyme B." (PMID 22400040, 2012). "Moreover, Bcl-2 inhibitors may be especially useful in tumours where the perforin/granzyme-B system is the main functional pathway available for target cell killing." (PMID 17311012, 2007). "Tumor-derived CD8+ T cells maintained cytokine secretion capacity and showed lower expression of TIM-3 and LAG-3, together with higher Granzyme B levels." (PMID 42096379, 2026). "Collectively, these data identify a subset of tumor-restraining, pro-immunogenic lymphocytes—CD8+GzmB+, CD4+IFN-γ+, CD103+ TRM, and CD69+ memory cells—whose activation predicts favorable outcomes and treatment responsiveness." (PMID 41562715, 2026). "AT3-OVA-ER cells showed less T cell–mediated killing than did AT3-OVA control cells in the different tumor/effector (T/E) ratios, along with a reduction of T cell activation (CD69) and cytotoxic markers (IFN-γ and granzyme B [GZMB])." (PMID 41289011, 2026). "Our syngeneic and carcinogen-induced CRC models demonstrated that Nat10 ablation enhances CD8+ T cell–dependent tumor control, as evidenced by increased cytotoxic CD8+ T cell infiltration, GzmB/IFN-γ production, and tumor regression." (PMID 41542770, 2026). "CD8+ T cell-specific Topk deletion increased granzyme B (GzmB), tumor necrosis factor-α (TNF-α), and interferon-γ (IFN-γ) secretion and improved tumor control." (PMID 41868885, 2026). "Results indicated that the T cell activation markers GZMB and IFN-γ were significantly increased in the tumor, while the immunosuppressive factor FOXP3 was significantly reduced following curcumin treatment." (PMID 41522360, 2026). "Our results demonstrated that the cytotoxic and anti-tumor activities of CAR-T cells were significantly increased post ITK inhibition treatment through elevation of cytotoxic and effector molecules, such as GZMB, TNF-α and IFN-γ." (PMID 41792111, 2026). "In an orthotopic murine model, DB Exo suppress tumor burden by ∼72% and remodel the BMM by increasing cytotoxic T-lymphocyte infiltration and elevating serum IFN-γ and Granzyme B levels." (PMID 42138792, 2026). "Tumor microenvironment and immune cell infiltration markers (CD3+, CD4+, CD8+, IFN-γ, granzyme B) were analyzed via flow cytometry and immunofluorescence." (PMID 41798950, 2026). "We assessed granzyme B expression in CD8+ T-cells isolated from the tumors, tumor-draining lymph nodes, and spleens of MOC2 tumor-bearing mice across all treatment groups." (PMID 41431358, 2026).
tumor (continued). "Although there were fewer immunocytes in the regressing tumor, there was also a decrease in the CD4:CD8 ratio and an increase in the intratumoral GzmB:CD3 ratio, suggesting that STR was driven by cytotoxic CD8+ T-cells." (PMID 40594889, 2025). "On The other hand, we identified a complex interplay involving CD36, CXCL11, GZMB, MT2 A, and CD8 + T cells that regulates immune function and tumor cell cycle processes." (PMID 40382758, 2025). "As we known, once CD8 + T cells are activated, they secrete Granzyme B and IFN-γ, two key molecules that work together to enable these cells to combat infections, manage tumor growth, and fine-tune immune regulation." (PMID 41330897, 2025). "Consistently, TZ‐dSA3‐12 enhanced the production of effector molecules, including GzmB and IFN‐γ, by tumor‐infiltrating CD8+ T cells compared to monotherapy, reinforcing its role in augmenting cytotoxic CD8+ T cells activity." (PMID 40492586, 2025). "Both in vivo and ex vivo fluorescence signals correlate with GzmB expression and activity, and the population of CD8+ cells in tumor tissues." (PMID 40161750, 2025). "While most anti-tumor effects of DCs occur through their activation of cytotoxic cells, DCs can also directly signal to tumor cells and induce cell death through TRAIL, nitric oxide, perforin, granzyme B and TNFα." (PMID 40663561, 2025). "Conversely, the naïve C57BL/6 mice for the construction of Model 2 displayed a naturally anti‐tumour effector of immune status (higher CD8+, higher CD4+, higher GZMB+, but higher PD1+)." (PMID 40356247, 2025). "After sorting tumour CD8(+)T cells using magnetic bead, perforin, granzyme A, and granzyme B expression were assessed by qRT‐PCR and ELISA." (PMID 39865544, 2025). "To assess the number and function of T cells within mouse xenograft tumors, we carried out IHC staining of xenograft tumor tissue sections using human CD3 antibody and human Granzyme B antibody." (PMID 40000620, 2025). "After tumor challenge, Sert-KO mice displayed significantly suppressed tumor growth and possessed increased numbers of tumor-infiltrating CD8 T cells exhibiting enhanced effector function (i.e., increased Granzyme B production)." (PMID 40403728, 2025). "Tumor cells usually express βF1 (TCR-β), cytotoxic proteins such as TIA-1, granzyme B, and perforin, and exhibit a high Ki-67 proliferation index (>75%)." (PMID 41227238, 2025). "T cell-predominant models require different approaches, as T cell-engaging tumor organoid platforms showed enhanced CD8+ T cell activation with increased interferon-gamma (IFN-γ) and granzyme B (GZMB) expression when treated with epigenetic inhibitors." (PMID 41155895, 2025). "Activation of the NKG2D/MICA signaling axis subsequently enhances NK cells expression of perforin, granzyme B, and NKG2D, improving their ability to kill tumor cells." (PMID 40557764, 2025). "Consistently, EZH2i promoted T cells activation (Granzyme B, IFNγ) and inhibited their exhaustion (LAG3) in tumor treated with chemotherapy, with similar phenomena as chemoimmunotherapy." (PMID 40708008, 2025). "Blood‐circulating CD8 T cells showed IFN‐γ and granzyme B (GrB) hyperfunction in response to anti‐CD3/28 stimulation, as well as impaired responses to ectopic tumour challenge and anti‐PD‐1/CTLA‐4 immunotherapy." (PMID 40760842, 2025). "Cells isolated from the spleens and tumor tissues were stained for surface markers (CD45, CD3, CD4, and CD8) and intracellular markers (granzyme B, IFN-γ, TNF-α, and FoxP3)." (PMID 40969744, 2025). "Exosomes derived from these CAR-T cells carrying PRF1 and GZMB exhibited high cytotoxicity against TNBC cell lines and reduced tumor volumes in xenograft models, highlighting the potential of exosome-mediated therapy in TNBC." (PMID 40281554, 2025). "Early stages of tumor growth were marked by robust T cell activation, including expression of cytotoxic mediators such as PRF1, GZMB, and IFN-γ, and dynamic polarization supported by IL-12 and STAT4." (PMID 41278869, 2025).